SOX12 (SRY-box transcription factor 12)
Description:
Transcription factor that binds to DNA at the consensus sequence 5'-ACCAAAG-3' (By similarity). Acts as a transcriptional activator (By similarity). Binds cooperatively with POU3F2/BRN2 or POU3F1/OCT6 to gene promoters, which enhances transcriptional activation (By similarity). Involved in the differentiation of naive CD4-positive T-cells into peripherally induced regulatory T (pT reg) cells under inflammatory conditions (By similarity). Binds to the promoter region of the FOXP3 gene and promotes its transcription, and might thereby contribute to pT reg cell differentiation in the spleen and lymph nodes during inflammation (By similarity). Plays a redundant role with SOX4 and SOX11 in cell survival of developing tissues such as the neural tube, branchial arches and somites, thereby contributing to organogenesis (By similarity).
Synonyms: SOX22
Tractability: PROTAC: ubiquitination databases record sites on it.
Gene: Protein-coding gene on chromosome 20 (325,552 to 330,224, forward strand). Ensembl gene ENSG00000177732.
Subcellular location: Nucleus
Subcellular location (Human Protein Atlas): Nucleoplasm
Gene Ontology:
Molecular function: sequence-specific double-stranded DNA binding; DNA binding; DNA-binding transcription activator activity, RNA polymerase II-specific; DNA-binding transcription factor activity, RNA polymerase II-specific; RNA polymerase II cis-regulatory region sequence-specific DNA binding; transcription cis-regulatory region binding
Biological process: brain development; camera-type eye morphogenesis; negative regulation of transcription by RNA polymerase II; neuron differentiation; positive regulation of regulatory T cell differentiation; positive regulation of transcription by RNA polymerase II; spinal cord development
Cellular component: nucleoplasm; nucleus; chromatin; protein-DNA complex
Genetic constraint (gnomAD): Loss-of-function variants: 8 observed, 16.23 expected, observed/expected ratio (o/e) 0.49, 90% interval 0.29 to 0.89. The synonymous counts are far from expectation, so gnomAD's model fits this gene poorly and the ratio says little. Missense variants: 400 observed, 377.07 expected, observed/expected ratio (o/e) 1.06, 90% interval 0.98 to 1.15. Synonymous variants: 235 observed, 179.24 expected, observed/expected ratio (o/e) 1.31, 90% interval 1.18 to 1.46.
Homologues: Orthologues: chimpanzee SOX12 (100% identical), dog SOX12 (97% identical), pig SOX12 (97% identical), mouse Sox12 (95% identical), rat Nrsn2 (95% identical), guinea pig SOX12 (92% identical), Drosophila melanogaster Sox14 (29% identical), Drosophila melanogaster Sox21a (24% identical), Drosophila melanogaster Sox100B (24% identical), zebrafish sox19b (21% identical), Drosophila melanogaster Sox15 (20% identical), zebrafish sox19a (20% identical), and 4 more. Paralogues in human: SOX4 (49% identical), SOX11 (42% identical), SOX7 (26% identical), SOX10 (26% identical), SOX9 (25% identical), SOX17 (25% identical), SOX8 (23% identical), SOX2 (23% identical), SOX1 (23% identical), SOX3 (23% identical), SOX14 (22% identical), SOX18 (22% identical), and 8 more.
Diseases named in the same sentence as SOX12 in open-access papers:
SOX12 is named in the same sentence as 48 diseases in open-access papers, as found by Europe PMC text mining. Sharing a sentence is not in itself a finding about the gene and the disease. The quoted sentences say what the papers report.
hepatocellular carcinoma (12 papers, 2019 to 2025). A malignant tumor that arises from hepatocytes. "In hepatocellular carcinoma cells, overexpression of SOX-12 can induce EMT, invasion, and metastasis, which is also considered to be a potentially promising target for this disease." (PMID 39184399, 2024). "SOX12 was identified to be abnormal expressed in various cancers, such as hepatocellular carcinoma, CRC and lung cancer." (PMID 36266695, 2022). "It was reported that SOX12 was upregulated and contributed to the initiation and progression of several cancers, such as gastric cancer, colorectal cancer, hepatocellular carcinoma, and lung cancer." (PMID 34745940, 2021). "It was reported that SOX12 played a crucial role in the maintenance of hepatocellular carcinoma metastasis." (PMID 34745940, 2021). "SOX12 can promote cisplatin resistance in hepatocellular carcinoma." (PMID 40592832, 2025). "LINC00978/microRNA-125b-5p/SOX12 axis promoted liver cancer migration, invasion, and proliferation, which could be used as a possible therapeutic target for the treatment of hepatocellular carcinoma." (PMID 35485164, 2022). "Importantly, SOX12+ hepatocellular carcinoma cells are more chemoresistant to cisplatin." (PMID 40592832, 2025). "Transforming growth factor‐β1 (TGF‐β1)‐stimulated SOX12 overexpression remodels the immunosuppressive microenvironment of hepatocellular carcinoma (HCC), promoting tumor progression and metastasis." (PMID 39072947, 2024). "Interestingly, key hepatoma genes such as SOX12 were upregulated when WNT was reactivated under OsmG conditions, suggesting that WNT might control the bridge between stemness and maturation." (PMID 38037844, 2024). "Thus, LINC00978/microRNA −125b-5p/SOX12 axis may be a new target for the management of hepatocellular carcinoma." (PMID 35485164, 2022). "As shown in the previous study, SOX12, a direct target of FOXQ1, promotes hepatocellular carcinoma (HCC) metastasis by upregulating Twist1 and FGFBP116." (PMID 30858360, 2019). "In addition to hepatocellular carcinoma, NR2F1-AS1 was also demonstrated to regulate the miR-423-5p/SOX12 axis to promote the proliferation and invasion of papillary thyroid carcinoma cells." (PMID 34738863, 2021).
breast carcinoma (8 papers, 2017 to 2024). "Taken together, miR-125b-5p directly suppressed the expression of SOX12 by binding to the 3′-UTR region in breast cancer cells." (PMID 34745940, 2021). "GSEA based on the dataset from TCGA suggested that a high SOX12 expression was related to tumor metastasis in breast cancer." (PMID 34745940, 2021). "Pearson’s correlation analysis confirmed a positive relationship between the expression levels of LGALS8-AS1 and SOX12 in TCGA database and in breast cancer tissues." (PMID 34745940, 2021). "In breast cancer cells, overexpression of SOX12 partially improved the inhibitory effect on cell proliferation, migration and invasion." (PMID 34712617, 2021). "For example, the upregulation of SOX12 has been reported to promote cancer proliferation or migration in colorectal, lung, liver, gastric, and breast cancers." (PMID 34442467, 2021). "The LGALS8-AS1/miR-125b-5p/SOX12 reciprocal regulatory loop dyscrasia promoted the migration and invasion of breast cancer cells." (PMID 34745940, 2021). "We analyzed the dataset from TCGA and concluded that the expression of SOX12 in breast cancer tissues was higher than that in normal tissues, which was further verified by the RT-qPCR analysis and Western blot assay in clinical samples." (PMID 34745940, 2021). "In contrast, SOX12 silencing suppresses the proliferation and metastasis of breast cancer and lung cancer." (PMID 30858360, 2019). "Furthermore, knockdown of SOX-12 expression suppresses the growth, migration, and invasion of lung and breast cancer cells." (PMID 39184399, 2024). "Moreover, the results of Pearson’s correlation analyses indicated a negative correlation between the expression levels of miR-125b-5p and SOX12 in breast cancer." (PMID 34745940, 2021). "Recent data demonstrated that SOX12 was related to prognostic survival in breast cancer." (PMID 34745940, 2021). "Also, SOX12 was significantly increased in breast cancer, and overexpression of SOX12 predicted a poor clinical outcome of patients." (PMID 34868396, 2021). "In addition, LGALS8-AS1 could activate the PI3K/AKT pathway and was feedback loop transcriptionally regulated by SOX12 in breast cancer." (PMID 34745940, 2021). "However, there are only a few studies on the effect of SOX12 on breast cancer metastasis." (PMID 34745940, 2021). "In total, seven TFs (HOXC11, FOXA1, SPDEF, SOX12, HOXC10, GATA3 and TFAP2A) were annotated to the breast cancer samples." (PMID 34712617, 2021). "For instance, Sox12, together with Sox11 and Sox4, is a member of the SoxC TF family, of which Sox4 has an established role in EMT and breast cancer progression." (PMID 29079737, 2017). "It upregulated SOX12 via competing as a competing endogenous RNA (ceRNA) for sponging miR-125b-5p and acted on the PI3K/AKT signaling pathway to promote the metastasis of breast cancer." (PMID 34745940, 2021).
colorectal cancer (6 papers, 2019 to 2025). A primary or metastatic malignant neoplasm that affects the colon or rectum. "GOT2 was reported by Du et al32 that ectopic expression of GOT2 could attenuate the SOX12 knock‐down‐induced suppression of colorectal cancer progression." (PMID 32285560, 2020). "However, the role of SOX12 and the mechanism by which it is dysregulated in colorectal cancer (CRC) remain unclear." (PMID 30858360, 2019). "In this context, SOX12 was identified as an important regulator of GOT2 and ASNS, and knockdown of either one of these enzymes suppressed SOX12-mediated proliferation and metastasis in colorectal cancer." (PMID 35205650, 2022).
gastric cancer (6 papers, 2021 to 2025). A primary or metastatic malignant neoplasm involving the stomach. "Increased expression of SOX12 was related to gastric cancer cell migration, invasion, and metastasis via transcriptionally targeting matrix metallopeptidase 7 (MMP7) and insulin-like growth factor 1 (IGF1)." (PMID 34745940, 2021). "In addition, SOX12 can promote gastric cancer metastasis by up‐regulating MMP7 and IGF1." (PMID 41425852, 2025). "IGF1 induced SOX12 expression via the PI3K/AKT/CREB pathway, forming an IGF1/CREB/SOX12 feedback loop that contributed to gastric cancer metastasis." (PMID 40638546, 2025). "SOX12 transcriptionally targets matrix metallopeptidase 7 (MMP7) and insulin-like growth factor 1 (IGF1) to facilitate gastric cancer metastasis." (PMID 35485164, 2022).
pancreatic cancer (6 papers, 2019 to 2025). "LncRNA C9orf139 could promote the growth of pancreatic cancer cells by targeting the miR-663a/Sox12 axis, which is a risk factor for prognosis of pancreatic cancer." (PMID 36561322, 2022). "In particular, the poor prognostic value of SOX11 expression in pancreatic cancer and sarcoma and SOX12 expression in breast and ovarian cancer as well as sarcoma, has not been reported previously." (PMID 34442467, 2021). "Evidence has been obtained that SOX12 may contribute to pancreatic cancer cell proliferation, migration, and invasion also through long noncoding and microRNAs mechanisms." (PMID 40141294, 2025). "It promotes pancreatic cancer cell growth by mediating the miR-663a/sox12 axis." (PMID 37702097, 2023).
leukemia (5 papers, 2017 to 2024). A malignant (clonal) hematologic disorder, involving hematopoietic stem cells and characterized by the presence of primitive or atypical myeloid or lymphoid cells in the bone marrow and the blood. "SOX-12 has also been confirmed to be participate in the progression of leukemia via modulation of β-catenin expression and interference of TGF/Wnt pathway." (PMID 39184399, 2024). "SOX12 knockdown could inhibit the proliferation of leukemia cells in vitro and suppressed the leukemia initiation in a mouse model." (PMID 34745940, 2021). "Moreover, treatment of cells with l-asparaginase, which degrades asparagine and is used to treat leukemia, significantly reduced SOX12-induced CRC cell proliferation and metastasis, representing a potential therapeutic treatment for patients with CRC." (PMID 30858360, 2019).
lung carcinoma (5 papers, 2021 to 2025). "In lung cancer, SOX12 was found to be upregulated in cancerous samples, and loss of SOX12 in tumor cells suppressed proliferation, migration, and invasion in vitro but stimulated apoptosis of tumor cells." (PMID 34868396, 2021). "SOX12 was discovered as tumor progression and EMT promoting factor in breast and lung cancer, and as prognostic marker in lung cancer and renal cell carcinoma." (PMID 40141294, 2025). "Among the 20E-down-regulated genes in lung cancer cells, several of them are considered to be oncogenes, including Notch3, HSF1, mTOR, SOX12, KLF16 (Kruppel-like factor 16,), and others." (PMID 37233697, 2023).
colon carcinoma (4 papers, 2014 to 2022). "There are studies demonstrating the correlation of SOX12 expression dysregulation with the occurrence and development of colon carcinoma, squamous cell carcinoma of the esophagus, renal carcinoma, and AML." (PMID 36120594, 2022). "Our present results define novel functions of the TMED3 and SOX12 genes as in vivo suppressors of human colon cancer metastases in mice." (PMID 24920608, 2014). "To extend the findings in CC14 cells with TMED3 and SOX12 presented above, we used HT29 human colon cancer cells to test the effects of shTMED3 and shSOX12." (PMID 24920608, 2014). "Using a novel in vivo assay to identify metastatic suppressor functions, we have uncovered that SOX12 and TMED3 limit the metastatic spread and/or growth of human colon cancer cells in mice." (PMID 24920608, 2014). "In particular, another member of the SOXC family also expressed in colon cancer, SOX4, is a positive cofactor for WNT-TCF signaling, raising the possibility that SOX12 could share this activity." (PMID 24920608, 2014). "Indeed, whereas both the KD of SOX12 and TMED3 are effective in CC14 (with undetermined APC status in this non-clonal primary colon cancer cell population), TMED3 KD has diminished potency in comparison with KD of SOX12 in HT29." (PMID 24920608, 2014).
liver cancer (4 papers, 2020 to 2025). An epithelial or non-epithelial malignant neoplasm that arises from the liver. "In addition, how the virus or alcohol, gender and other risk factors aggravate the progress of liver cancer through SOX12 also needs our attention in the future." (PMID 32184801, 2020). "Recent studies have reported that SOX12 plays important roles in various tumors, e.g., SOX12 promotes liver cancer metastasis." (PMID 34725550, 2021). "Studies have also indicated that SOX12 is an important marker of liver cancer stem cells, whereas other studies have suggested that it promotes stemness in glioma cells." (PMID 34725550, 2021). "Moreover, the function of LINC00978/microRNA-125b-5p/SOX12 axis in liver cancer growth and metastasis was revealed, which can be used as a new marker and potential therapeutic target for HCC." (PMID 35485164, 2022). "However, the mechanistic relationship between SOX12 and viral-infected liver cancer need to be further explored." (PMID 32184801, 2020). "SOX12 increases intratumoral regulatory T-cell (Treg) infiltration and decreases CD8+ T-cell infiltration in liver cancer." (PMID 39889187, 2025).
papillary thyroid carcinoma (4 papers, 2020 to 2025). "NR2F1-AS1 also regulated miR-423-5p/SRY-box transcription factor 12 (SOX12) axis to promote the proliferation and invasion of thyroid papillary carcinoma cells." (PMID 34738863, 2021). "LncRNA NR2F1-AS1 regulated miR-423-5p/SOX12 to promote proliferation and invasion in papillary thyroid carcinoma." (PMID 33505907, 2020). "However, the precise function of SOX12 in papillary thyroid carcinoma (PTC) metastasis remains to be investigated." (PMID 40593465, 2025). "In papillary thyroid carcinoma, NR2F1-AS1 acted as an oncogene by sponging miR-423-5p to upregulate SOX12 expression." (PMID 34335755, 2021).
cervical cancer (3 papers, 2022 to 2023). A primary or metastatic malignant neoplasm involving the cervix. "In cervical cancer, both in vitro and in vivo studies have shown that SOX12-induced SNHG15 promotes cervical cancer tumorigenesis and resistance to cisplatin via the miR-4735-3p/HIF1a pathway." (PMID 37056344, 2023). "SOX12 enhances the Tumorigenic Properties and Chemoresistance in Cervical Cancer by targeting lncRNA SNHG15/miR-4735-3p/HIF1a Pathway." (PMID 35485164, 2022).
developmental delay (3 papers, 2016 to 2024). "Although no neurodevelopmental disorders have been directly attributed to defects in the SOX12 gene thus far, it has been implicated as a candidate gene in developmental delay." (PMID 39057025, 2024). "As outlined, SOX12 has been identified as a candidate gene involved in developmental delay in a microdeletion of 20p13, which includes SOX12 along with another gene." (PMID 39057025, 2024). "This deletion included SOX12 and NRSN2, both of which have been identified as pivotal genes associated with developmental delays." (PMID 31087544, 2019). "Interestingly, we found that most of the affected patients with developmental delays were caused by the defects of multiple genes which were usually associated with TBC1D20, SOX12, and NRSN2 genes." (PMID 31087544, 2019). "This microdeletion involved SOX12 (OMIM#601947) and NRSN2 (OMIM#610666), which were previously reported to induce developmental delays in patients with 20p13 microdeletions." (PMID 31087544, 2019).
ovarian carcinoma (3 papers, 2021). A malignant neoplasm originating from the surface ovarian epithelium. "Increased SOX12 expression was observed in breast, esophageal, lung, and ovarian cancers as well as sarcoma, compared to that in their corresponding normal tissues, using the Oncomine database." (PMID 34442467, 2021). "miR-138 inhibits the occurrence and development of ovarian cancer by downregulating the expression of SOX12 gene and invasion via SOX4 and HIF-1α oncogenic transcriptional factors." (PMID 33673181, 2021).
acute myeloid leukemia (2 papers, 2021 to 2022). Acute myeloid leukemia (AML) is a group of neoplasms arising from precursor cells committed to the myeloid cell-line differentiation. "SOX12 has important roles in many tumors; a previous study indicated that SOX12 is a novel potential target for acute myeloid leukemia." (PMID 34725550, 2021).
Arthritis (2 papers, 2022 to 2023). Inflammation of a joint. "The functionally redundant activities of Sox4, Sox11 and Sox12 in TNF-induced arthritis and the diverse range of stimuli that can potentially activate the canonical NF-κB signaling in the FLS are suggestive of a role for multiple additional co-factors besides SOXC and RELA." (PMID 35529852, 2022). "SOX12 appears to have no role in arthritis, however SOX11 is dysregulated and promotes arthritic progression according to some studies but supports joint maintenance and protects cartilage and bone cells according to others." (PMID 36835620, 2023). "Based on the currently available data, SOX12 seems not to be involved in arthritis disease progression, while SOX11 is dysregulated and enhances arthritic progression according to some studies, but is required for joint maintenance and protects cartilage and bone cells according to other studies." (PMID 36835620, 2023).
generalized epilepsy (2 papers, 2024). Epilepsy that is characterized by generalized seizure types and may have typical interictal and/or ictal EEG findings that accompany generalized seizure types (for example generalized spike-wave). "Whole exome sequencing (WES) in patients presenting with generalized epilepsy, intellectual disability, and childhood emotional behavioral disorder, uncovered a de novo variation within SOX12 gene." (PMID 39057025, 2024).
glioma (2 papers, 2021 to 2022). A benign or malignant brain and spinal cord tumor that arises from glial cells (astrocytes, oligodendrocytes, ependymal cells). "Previous study had proved that HuR can not only bind to DUXAP10 but also SOX12 in glioma cells." (PMID 36053455, 2022).
Intellectual disability (2 papers, 2024). "The absence of detailed studies on SOX12 in relation to epilepsy, intellectual disability and childhood emotional behavioral disorders represents a critical gap in our knowledge." (PMID 39057025, 2024).